CASR (calcium sensing receptor)
Diseases named in the same sentence as CASR in open-access papers (continued):
Sharing a sentence is not in itself a finding about the gene and the disease.
tumor (continued). "The CaSR could act as the calcium sensor and become activated by the (presumed) high extracellular Ca2+; in bone tissue this would be followed in turn by activation of the associated integrins on the tumor cell to signal attachment to bone ECM proteins such as fibronectin and collagen." (PMID 27303307, 2016). "CaSR activation can also have diametrical consequences in normal and tumor cells as shown for mammary epithelial cells by activating different G-proteins." (PMID 27625611, 2016). "Altered CaSR expression occurs in benign and malignant tumors suggesting it as either a tumor suppressor or oncogene." (PMID 27679579, 2016). "This would be consistent with the active vitamin D metabolite exerting its antiproliferative, prodifferentiating effects in part by inducing expression of the tumor suppressor, CaSR." (PMID 27679579, 2016). "It has also become apparent that the CaSR is involved in additional processes including cellular differentiation and migration, brain development, stem cell engraftment, wound healing, and tumor growth and metastasis." (PMID 27303307, 2016). "Similar findings have been reported in colon cancer, where it has been proposed that activation of the CaSR inhibits tumor progression and enhances chemotherapeutic responses." (PMID 27746743, 2016). "The CaSR in part mediates the antiproliferative and prodifferentiation actions of Ca2+ in colonocytes and can be considered as a tumor suppressor in the colon." (PMID 27679579, 2016). "Activation of the CaSR in these tumors has been reported to decrease cell proliferation and tumor progression." (PMID 27303307, 2016). "In theory,downregulation of CASR levels would allow for a continuously reduced feedback, which wouldresult in both tumor growth and reduced calcium-mediated suppression of PTHgene expression." (PMID 26865585, 2016). "Calcium acts on tumour cells expressing the calcium-sensing receptor (CASR) by enhancing tumour cell survival." (PMID 27761364, 2016). "CaSR is considered as a molecule that can either promote or prevent tumor growth depending on the type of cancer." (PMID 27625611, 2016). "The expression of CaSR and smaller levels of parathyroid hormone-related protein were observed in differentiated, favourable neuroblastic tumours." (PMID 26010602, 2015). "In this study we present evidence that the CaSR is a tumor suppressor in the colon using three distinct approaches: ex vivo, in vivo and in vitro." (PMID 25701758, 2015). "In this study we aimed to decipher the mechanisms that contribute to the tumor suppressive functions of the CaSR during colorectal tumorigenesis." (PMID 25879211, 2015). "Since tumor cell spheroids are considered more representative of in vivo conditions, we evaluated the role of the CaSR in regulating migration and invasion of CRC cells in a 3D spheroid cell invasion assay." (PMID 25879211, 2015). "As > 90% of our patient cohort (51 out of 54) were of grade 2, and we had only one stage IV patient with distant metastasis, we were unable to assess a correlation between CaSR expression and tumor grade or stage." (PMID 25701758, 2015). "It has been suggested that the CaSR is either a tumor suppressor (e.g. in colon and parathyroid) or an oncogene (e.g. in breast and prostate) depending on the site of disease." (PMID 25701758, 2015). "Several model systems have provided convincing evidence for the role of the CaSR as a tumor suppressor in the colon." (PMID 25879211, 2015). "In samples of tumor tissue from our patient cohort, all analyzed regions of the CaSR promoter 2 showed increased DNA methylation when compared with the matched samples of apparently normal adjacent mucosa." (PMID 24691920, 2014). "In contrast to the expression of CaSR protein in tumor specimens with a 1.5-fold higher value (median) in patients with bone metastases compared to those without metastases, FACS analyses of primary cells showed a significant (p = 0.006) 3.9-fold higher value." (PMID 24576174, 2014).
tumor (continued). "CaSR mRNA expression levels were significantly lower in tumor tissues when compared with samples of the respective adjacent mucosa (n = 65, p < 0.001)." (PMID 24691920, 2014). "The CaSR promoter was higher methylated in samples of tumor tissue compared with the apparently normal adjacent mucosa from the same patient (n = 20, p < 0.01)." (PMID 24691920, 2014). "Since the CaSR expression was enhanced in tumor tissue and primary cells from patients who developed bone metastases, we investigated the influence of extracellular calcium in processes of metastasis." (PMID 24576174, 2014). "We found significant inverse correlation between methylation level of CaSR promoter 2 in tumor tissues and anatomical location of the primary tumor." (PMID 24691920, 2014). "The expression level of CaSR in primary RCC cells showed a pattern similar to that found in tumor tissue." (PMID 24576174, 2014). "The calcium-sensing receptor (CaSR) is a putative tumor suppressor gene in the colon, which partially mediates the anti-proliferative and pro-differentiating actions of calcium in colonocytes." (PMID 24176760, 2014). "Although CaSR antagonists exhibit antitumor activity in some tumors, in other tumor types CaSR may have an inhibitory effect and the use of CaSR antagonists may instead promote tumor growth (Saidak, Mentaverri & Brown, 2009)." (PMID 41522513, 2026). "The role of CaSR varies according to tumor type, cell microenvironment, and signaling pathway." (PMID 41522513, 2026). "In a variety of malignancies, abnormal activation of CaSR may promote tumor cell survival and invasion." (PMID 41522513, 2026). "While tumor cells can drive metabolically dependent proliferation by abnormally activating cholesterol synthesis pathways, our findings suggest that CaSR antagonism may modulate cholesterol biosynthesis-related pathways at the transcriptomic level." (PMID 41522513, 2026). "Moreover, we demonstrate that transfection of the CaSR into a PNET cell line reduces cell viability, thereby indicating that the CaSR acts as a tumour suppressor in this tumour type." (PMID 39579056, 2025). "Furthermore, depending on the cellular context, the CaSR has been reported to act as both an oncogene and tumour suppressor." (PMID 39579056, 2025). "Notably, emerging studies show bone-metastatic tumors can, via self-reinforcing vicious cycles and calcium-sensing receptor upregulation, promote tumor proliferation and skeletal tropism, thereby accelerating metastatic progression." (PMID 41149453, 2025). "Based on this evidence, it may be expected that CaSR expression would be lost in non‐functioning tumours but maintained in functioning tumours." (PMID 39579056, 2025). "In 70 women with uterine myomas, CaSR was determined in the tumor and its periphery." (PMID 39000274, 2024). "Besides its primary function in the control of calcium homeostasis, the CaSR also has tumor suppressor functions as it can regulate inflammation, cell proliferation, cell differentiation and apoptosis." (PMID 39233917, 2024). "Parathyroid gland emerges as a novel target of the bone secreted hormone osteocalcin, which may modulate tumor parathyroid CASR sensitivity and parathyroid cell apoptosis." (PMID 37065733, 2023). "These discrepancies of the roles of CaSR on tumor progression in different cancers imply that it might be tissue or disease specific." (PMID 36348350, 2022). "This reduced sensitivity of the CaSR may not only blunt the response of tumor cells to circulating Ca2+ but also facilitate the growth and motility of tumor cell via cytosolic Ca2+ mediated processes." (PMID 35355564, 2022). "In both responsive animal models, tumor-growth inhibition came along with an upregulation of CaSR expression, corroborating previously published data, demonstrating that calcimimetics modulate both the expression and activity of CaSR." (PMID 35457141, 2022). "IHC analyses showed that CaSR expression was enhanced in the tumor tissues." (PMID 36348350, 2022).
tumor (continued). "Moreover, the role of extracellular Ca2+ and CaSR in cancers has been identified, promoting tumor cell proliferation, migration, and bone metastasis." (PMID 36071984, 2022). "However, in AtT20 cells, CaSR activates a tumour-specific cAMP pathway that promotes ACTH and PTHrP hypersecretion." (PMID 34223822, 2021). "Besides its role in calcium homeostasis, the CaSR plays additional roles in several tissues, including several tumor types." (PMID 34357109, 2021). "Of all the factors released during bone resorption, matrix-derived growth factors can aid tumor cell survival and/or PTHrP production, feeding the cycle of osteolysis and thus, investigating the CaSR-PTHrP axis might open doors on a therapeutic front." (PMID 32117726, 2020). "The data showed that tumor volumes and weights increased prominently (∗p < 0.05), either by decreasing CaSR protein expression (shRNA-CaSR group vs. empty vector group), or by decreasing CaSR activity (NPS 2143 group vs. blank control group)." (PMID 32671062, 2020). "SNR and SE% (calculated as [(SNR-SNR0)/ SNR0]×100) for all tumour lesions respectively, of xenotransplant and pseudometastatic tumour animal model, before and 90 minutes after manganese administration and CaSR or TRPV6 expression levels evaluated by immunohistochemistry." (PMID 32931488, 2020). "Although we will be focusing on the mammary gland, it is important to keep in mind the tissues where the CaSR aids tumor progression; cumulative evidences of similar function in different tissues would help us decipher the intricacies of the signaling aspects of the CaSR." (PMID 32117726, 2020). "Tumor cells with a high expression of CaSR are recruited to reach local bone tissue via EMT and directly or indirectly act on OCs in the bone microenvironment, which disrupts the balance of bone metabolism, promotes OC differentiation and maturation, and forms new bone metastases." (PMID 32269963, 2020). "Thus, we suggest that in different tumors, CaSR-mediated irregular oscillation activates different transcription factors and therefore regulates tumor cell growth or other biological behaviors in different ways." (PMID 32671062, 2020). "In the “vicious cycle” fueled by tumor cells that leads to a disrupted osteoblast-osteoclast coupling, the CaSR may also serve as a target on osteoclasts." (PMID 32117726, 2020). "The CaSR seems to function as an oncogene or tumor suppressor gene based on the cancer site." (PMID 32117726, 2020). "CaSR is a G protein coupled receptor, which plays an important role in tumour development." (PMID 32931488, 2020). "Furthermore, ablating the CaSR in MMTV-PyMT (mouse mammary tumor virus-polyoma middle tumor-antigen) transgenic mouse model tumor cells promoted apoptosis and inhibited growth ex vivo." (PMID 32117726, 2020). "CaSR can promote PTHrP secretion when it is upregulated in the tumor cell." (PMID 32269963, 2020). "The overall accumulation of Mn2+ could thus be due to the combined effect of perfusion due to the level of tumour vascularity and CaSR activity." (PMID 32931488, 2020). "In addition, patients with a tumour harbouring a CDC73 mutation, or loss of CASR or parafibromin expression presented worse survival outcomes." (PMID 31142320, 2019). "Moreover, the release of Ca2+ during normal bone remodeling binds with CaSR, a calcium-sensing receptor to stimulate parathyroid hormone-related protein (PTHrP), that leads to tumor cell reactivation." (PMID 30823602, 2019). "Understanding the interplay between PTH1R and CaSR signaling in the development of BrCa bone metastases could lead to a novel therapeutic approach to control both osteolysis and tumor burden in the bone." (PMID 30151009, 2018). "Therefore, the interplay of PTH1R and CaSR acts in concert to evoke excessive bone destruction and progressive tumor growth." (PMID 30151009, 2018).
tumor (continued). "This supports the hypothesis that expression of CaSR guides the tumor cells to the bone and emphasized the organ-specific metastasis of tumor cells." (PMID 29644008, 2018). "Tumor cells harboring the calcium-sensing receptor could enhance these cellular processes downstream via the integrin signaling cascade and also via the CaSR signaling cascade itself." (PMID 29644008, 2018). "Our results support the hypothesis that CaSR guides the tumor cells to the bone and the development of organ-specific metastasis of tumor cells." (PMID 29644008, 2018). "Importantly, BrCa cells spread to the skeleton and express more CaSR than the cells in the primary tumor do." (PMID 30151009, 2018). "Finally, the role of CaSR in digestive, respiratory, cardiovascular and neoplastic diseases is gradually coming to light, providing new therapeutic possibilities." (PMID 28122587, 2017). "However, the intracrine CaSR-nuclear PTHRP pathway that directly stimulates tumor cell proliferation and allows the cells to survive in spite of the elevated extracellular calcium concentrations is also promoted." (PMID 29099748, 2017). "In fact, the effects of the CaSR activation on tumor growth should be due to the increased PTHRP value that at nuclear level reduces the expression of the cell cycle inhibitor p27kip1 and prevents nuclear accumulation of apoptosis-inducing factor (AIF), which promotes apoptosis." (PMID 29099748, 2017). "As the CaSR mediates most of the tumor preventive effects of [Ca2+]o, the level of the CaSR could become a marker for the responsiveness to the anti-proliferative effect of [Ca2+]o." (PMID 28161520, 2017). "This phenomenon may result both from the high level of epiregulin expressed in CaSR-WT-transfected cells and the increased tumor burden observed in response to high CaSR activity." (PMID 28915604, 2017). "This indicates that, although CaSR plays a role in Mn uptake in tumour cells via its ion-channel regulation, the T1 shortening effect of Mn2+ on MRI could not be explained solely by ion-channel activity." (PMID 29708197, 2017). "This raises the issue that the development of CaSR therapeutics as applied to oncology could be complicated by the possibility of a CaSR drug promoting tumor cell proliferation while inhibiting metastasis, or vice versa." (PMID 27303307, 2016). "Our findings also suggest that CaSR signaling can increase intracrine/nuclear signaling by PTHrP and directly stimulate tumor cell proliferation and enhance the ability of the cells to survive in the face of the elevated extracellular calcium concentrations resulting from active bone resorption." (PMID 27746743, 2016). "In any case, a more thorough analysis of CaSR pharmacology, expression levels, and signaling mechanisms in tumor cell biology could ultimately provide solutions that translate into novel therapeutic applications." (PMID 27303307, 2016). "In this context, could stimulating CaSR activity via positive allosteric modulators or calcimimetics hinder tumor cell proliferation, and conversely, could inhibiting CaSR activity via calcilytics or receptor knockdown, block or stymie cancer metastasis?" (PMID 27303307, 2016). "In this instance the CaSR appears to indirectly regulate the migration and morphogenesis of endothelial cells and may contribute to tumor neovascularization." (PMID 27746743, 2016). "Therefore, among many other functions of the NS in which it participates, this mini-review focuses on the role of CaSR in differentiation, a cellular process that is crucial for both normal development and tumor biology." (PMID 27242543, 2016). "We postulate that in circulating tumor cells, CaSR-integrin protein complexes could function together as a cell surface detection mechanism for attaching to the ECM components of the bone microenvironment." (PMID 27303307, 2016).
tumor (continued). "The CaSR has been shown to form signaling complexes with the integrins to facilitate both the movement and differentiation of cells, such as neurons during normal brain development and tumor cells under pathological circumstances." (PMID 27303307, 2016). "Thesecases also had significantly higher levels of tumor CASR expression." (PMID 26865585, 2016). "Different regions of a single tumor can manifest distinct patterns of CASR protein localization, with certain areas displaying the predominantly membrane-bound pattern typical of normal tissue co-existing with other areas where CASR is absent or concentrated in cytoplasmic structures." (PMID 27537691, 2016). "Interestingly, tumor CASR protein levels have previously been coupled to thedegree of shift in the calcium–PTH set point, but not to tumor size." (PMID 26865585, 2016). "Our results demonstrate a critical tumor suppressive role of CaSR in the colon." (PMID 25701758, 2015). "Expression of the calcium-sensing receptor (CaSR), a calcium-binding G protein-coupled receptor is downregulated in CRC leading us to hypothesize that the CaSR has tumor suppressive roles in the colon." (PMID 25701758, 2015). "We show that both of these factors are increased in cells expressing functional CaSR supporting the hypothesis that downregulation of the CaSR is coupled to tumor dedifferentiation in CRC." (PMID 25701758, 2015). "Therefore the disposition for bone metastasis is possibly already determined in healthy tissue, or alternatively, the primary tumor induces enhanced CaSR in normal renal tissue." (PMID 24576174, 2014). "Inducing expression of CaSR, a putative tumor suppressor in the colon, might be one of the tumor preventive mechanisms of 1,25D3." (PMID 24176760, 2014). "In normal renal tissue, CaSR expression was considerably higher than in tumor specimens." (PMID 24576174, 2014). "Altogether, these data were consistent with the hypothesis that the CaSR exerts tumor-suppressor functions in the context of neuroblastic tumors." (PMID 23533647, 2013). "Our results suggest that the LCT 13910 CC genotype may affect tumor recurrence and disease-free survival, while the modified calcium signaling in the CaSR 986 SS genotype could lead to increased incidence of CRC." (PMID 18980667, 2008). "Therefore, we hypothesize that CaSR may affect the cisplatin resistance of tumor cells through its effects on cyclin B1 and BRCA1." (PMID 39113697, 2024). "Interestingly, CaSR is not only expressed on tumor cells, but also exists in T lymphocytes." (PMID 36348350, 2022). "Therefore, we speculate that spermine may directly activate CaSR in T lymphocytes and induce the apoptosis of T lymphocytes, leading to immune escape of tumor cells in HCC." (PMID 36348350, 2022). "Previous documents suggest that CaSR may possess possible roles as either a tumor promoter or a tumor suppressor in different organs, since CaSR regulates various pathophysiological processes, including cell proliferation, differentiation, etc. in a tissue-dependent manner." (PMID 32671062, 2020). "Skeletal tumor burden in the intratibial cavity of mice injected with CaSR-WT-transfected cells appeared significantly more pronounced as compared to mice injected with EV- or CaSR-DN-transfected cells, due to replacement of bone tissue and bone marrow with tumor cells." (PMID 28915604, 2017). "Together, these data suggest that the large amounts of Ca2+ released after PTHrP-induced bone resportion could 1/ facilitate tumor cell migration into the bone through CaSR stimulation and 2/ participate to the vicious circle of bone resorption through CaSR induced-PTHrP secretion." (PMID 28915604, 2017). "In addition to its well characterized role in maintaining calcium homeostasis and regulating parathyroid hormone release, evidence has accumulated linking the CaSR with cellular differentiation and migration, brain development, stem cell engraftment, wound healing, and tumor growth and metastasis." (PMID 27303307, 2016).